NPTX2 (neuronal pentraxin 2)
Diseases named in the same sentence as NPTX2 in open-access papers (continued):
Sharing a sentence is not in itself a finding about the gene and the disease.
Headache (2 papers, 2024 to 2025). Cephalgia, or pain sensed in various parts of the head, not confined to the area of distribution of any nerve. "A strong association was found between headache and CpG methylation in the SHD5 and NPTX2 genes, which are responsible for the regulation of synaptic plasticity." (PMID 39590352, 2024). "Novel mechanisms were proven to be exerted by ZOL in ameliorating migraine headache and pain such as decreasing the gene expression of key epigenetically altered genes in migraine; RAMP-1 and NPTX-2, and modulation of the endocannabinoid; CB-1/MAPK pathway." (PMID 39500819, 2025).
hippocampal atrophy (2 papers, 2020 to 2022). "In addition to its essential role at the synapse, low CSF NPTX2 levels are associated with hippocampal atrophy, supporting its role as a biomarker of synapse dysfunction." (PMID 35338546, 2022).
Intellectual disability (2 papers, 2020 to 2025). "We compared group differences in CSF NPTX2 according to clinical diagnosis and degree of intellectual disability." (PMID 32807227, 2020). "The lack of association of NPTX2 levels with intellectual disability suggests that the reduction in NPTX2 levels is not neurodevelopmental." (PMID 32807227, 2020). "Taken together, we propose that changes in CSF NPTX2 levels in adults with DS are related to AD pathophysiology and not to intellectual disability." (PMID 32807227, 2020).
ischemic stroke (2 papers, 2025). A stroke disorder caused by obstruction of blood flow to the brain, due to thrombotic (local blood clot formation) or embolic (due to a blood clot or other material traveling from another site) event. "Investigations in an ischemic stroke rat model suggested that the induced clustering of AMPA receptors by NPTX2 leads to their internalization, resulting in reduced response to glutamate, reflecting a rescue mechanism." (PMID 40868076, 2025). "Thus, upregulation of NPTX2 may protect neurons from glutamate excitotoxicity in environments with excess of glutamate in the synaptic cleft as in ischemic stroke, but also in adult SMA." (PMID 40868076, 2025).
liver cancer (2 papers, 2022 to 2025). An epithelial or non-epithelial malignant neoplasm that arises from the liver. "Although no consistent patterns for the Δβ of ALX3, NPTX2, and TRIM58 were observed across the stages, these three genes were stably hypermethylated in nearly all stages, except for NPTX2 at the fourth stage in liver cancer." (PMID 39944136, 2025).
migraine (2 papers, 2023 to 2025). "A larger study of epigenetic changes in SH2D5, NPTX2, COMT, GIT2, ZNF234, and SOCS1 genes is necessary to understand the processes of migraine chronicity and MOH development." (PMID 37298078, 2023). "Key epigenetically altered genes in migraine include RAMP-1 and NPTX-2 genes." (PMID 39500819, 2025). "The patch was finally examined in vivo to investigate possible novel mechanisms for the antimigraine action of ZOL via alternative pathways affecting the altered migraine chronification genes (RAMP-1, and NPTX-2), or microRNAs and modulation of the endocannabinoid; CB-1/MAPK pathway." (PMID 39500819, 2025). "Epigenome alteration may lead to the progression to chronic migraine (chronification of migraine), such as the altered methylation pattern of the receptor activity-modifying protein-1 (RAMP-1), and the neuronal pentraxin-2 (NPTX-2) genes." (PMID 39500819, 2025). "Results revealed a significant increase in the expression of NPTX-2 and RAMP-1 genes and a significant decrease in the miR-382-5p in the brain tissue of rats with NTG-induced migraines relative to normal rats without migraine induction (p < 0.001)." (PMID 39500819, 2025).
osteosarcoma (2 papers, 2021 to 2022). A usually aggressive malignant bone-forming mesenchymal neoplasm, predominantly affecting adolescents and young adults. "The expression of Neuronal pentraxin (NPTX2) is negatively correlated with the expression of GZMB and IFNG, Knockdown of NPTX2 in osteosarcoma cells inhibited tumor growth and increased tumor cell apoptosis." (PMID 36204682, 2022). "Analysis was performed to explore if NPTX2 affects the proliferation and apoptosis of osteosarcoma cells." (PMID 34258887, 2021). "In addition, in vitro experiments showed that NPTX2 expression influenced the biological behaviors of osteosarcoma cells." (PMID 34258887, 2021). "This suggests that NPTX2 disrupts immune response against osteosarcoma." (PMID 34258887, 2021). "Knockdown of NPTX2 in osteosarcoma cells inhibited tumor growth and increased tumor cell apoptosis." (PMID 34258887, 2021). "Notably, the local expression of CCL4 in tumor lesions was negatively correlated with the expression of NPTX2 in the TCGA datasets and in osteosarcoma patient samples." (PMID 34258887, 2021). "Accordingly, NPTX2 is a potential immunotherapeutic target for osteosarcoma." (PMID 34258887, 2021). "In addition, NPTX2 knockdown significantly increased the apoptosis rate in osteosarcoma cells." (PMID 34258887, 2021). "Therefore, targeting NPTX2 may offer a novel approach for the immunotherapeutic management of osteosarcoma." (PMID 34258887, 2021). "The knockdown of NPTX2 in HOS and SW1353 cells reduced cell proliferation, enhanced cell apoptosis, which demonstrates that NPTX2 may promote osteosarcoma progression." (PMID 34258887, 2021). "However, NPTX2 expression in osteosarcoma has not been reported." (PMID 34258887, 2021).
ovarian carcinoma (2 papers, 2021 to 2023). A malignant neoplasm originating from the surface ovarian epithelium. "In the present study, we found for the first time that NPTX2 was significantly upregulated in epithelial ovarian cancer and correlated with the poor prognosis." (PMID 33768003, 2021). "We then detected clinical specimens from ovarian carcinoma patients and found the similar NPTX2 expression as that in TCGA and GEO databases." (PMID 33768003, 2021). "In addition, we performed Kaplan-Meier survival analysis for the prognostic significance of NPTX2 expression in ovarian carcinoma patients, and the survival time of patients with high NPTX2 expression was significantly lower in the TCGA dataset than in patients with low expression." (PMID 33768003, 2021). "NPTX2 is the most significantly upregulated gene among these genes, while its biological role in ovarian cancer has not been reported." (PMID 33768003, 2021).
renal carcinoma (2 papers, 2022 to 2024). A carcinoma arising from the epithelium of the renal parenchyma or the renal pelvis. "The TCGA dataset revealed that expression of NPTX2 is different in distinct types of cancer, and NPTX2 may represent a prognostic marker in renal cancer and endometrial cancer." (PMID 35069913, 2022). "The Human Protein Atlas revealed moderate to strong cytoplasmic positivity for NPTX2 in rare carcinoid and renal cancers, while all remaining cancer tissues were negative." (PMID 38254821, 2024).
thymoma (2 papers, 2024). A neoplasm arising from the epithelial cells of the thymus. "The DNA methylation rate of the NPTX2 gene in thymoma B3 was midway be- tween those of the normal thymus and TC, while that in NECTT was low." (PMID 38254821, 2024). "Our genome-wide screening identified neuronal pentraxin 2 (NPTX2) as the 33rd significantly hypermethylated CGI in TC in relation to B3 thymomas." (PMID 38254821, 2024). "The DNA methylation rate of the NPTX2 gene in thymoma B3 was midway between the normal thymus and TC." (PMID 38254821, 2024). "ROC curves showing the accuracy of NPTX2 mRNA expression, used to differentiate TC from thymomas, revealed moderate sensitivity and specificity (AUC = 0.5755)." (PMID 38254821, 2024). "The DNA methylation rate of the NPTX2 gene was significantly higher in TC than in the normal thymus and thymomas, except B3." (PMID 38254821, 2024). "The DNA methylation level of NPTX2 was higher, while its mRNA and protein expression levels were lower in TC than in the normal thymus and thymoma." (PMID 38254821, 2024). "The accuracy of the DNA methylation signature of NPTX2 used to discriminate TC from thymomas was assessed using the ROC analysis, with AUC was used as the criterion for accuracy." (PMID 38254821, 2024). "In the present study, genome-wide screening was performed on aberrantly methylated CpG islands in TET, and this identified neuronal pentraxin 2 (NTPX2) as a significantly hypermethylated CpG island in TC relative to thymomas." (PMID 38254821, 2024). "The ROC curves for the accuracy of the NPTX2 methylation signature differentiate TC from thymomas." (PMID 38254821, 2024). "Similarly, the NPTX2 gene exhibited markedly higher methylation levels in TC compared to thymoma (38.0% vs. 17.5%), with notable sensitivity and specificity in terms of discriminating between TCs and thymomas." (PMID 38338833, 2024). "IHC was performed on 39 TET, including 18 thymomas, 18 TC, and 3 NECTT, to assess the NPTX2 protein expression level." (PMID 38254821, 2024). "The present results reveal that TET may be classified into three tumor types—thymoma, TC, and NECTT—according to the DNA methylation and gene expression of NPTX2." (PMID 38254821, 2024). "Furthermore, no variations in the DNA methylation of MT1A and NPTX2 were identified among the several histological types of thymoma based on the WHO histologic classification." (PMID 38338833, 2024).
amnesia (1 paper, 2025). Pathologic partial or complete loss of the ability to recall past experiences ( AMNESIA, RETROGRADE) or to form new memories ( AMNESIA, ANTEROGRADE). "That is to say, during aging, Nptx2 downregulation-induced disruption of local perisomatic inhibition in DG engram precedes Nptx1 downregulation-induced disruption of long-range MEC-DG excitatory projection; this probably explains why generalization always emerges before amnesia in aged individuals." (PMID 40750687, 2025).
astrocytic tumor (1 paper, 2022). A glial tumor of the brain or spinal cord showing astrocytic differentiation. "EGFR is the most frequently amplified oncogene in astrocytic tumors; expression of genes SRI, NPTX2, MEST, RARRES2, and SEPTIN7 in association with GBM is reported in this study." (PMID 35327982, 2022).
autism (1 paper, 2015). Persistent deficits in social interaction and communication and interaction as well as a markedly restricted repertoire of activity and interest as well as repetitive patterns of behavior. "Two inherited apparently balanced rearrangements mapping to this region have been reported in autism: a paracentric inversion (7q22.1q31.1) in two siblings with autism and a translocation involving chromosome 7q22.1, just distal to NPTX2, in a subject with autism and ID." (PMID 25844147, 2015).
colon tumour (1 paper, 2021). "In colon tumour cells, HIF-1α can regulate IL-6 expression via miR-338-5p.However, under hypoxic stress, the HIF-1 complex can promote the transcription and expression of neuronal pentraxin II (NPTX2)." (PMID 35004308, 2021).
delirium (1 paper, 2024). A disorder characterized by confusion; inattentiveness; disorientation; illusions; hallucinations; agitation; and in some instances autonomic nervous system overactivity. "Although SNAP-25 and NPTX2 did not exhibit significant differences in delirium, the exploration of synaptic biomarkers remains promising for enhancing our understanding of this condition." (PMID 38566855, 2024). "Significant differences were observed in the ratios of NFL and NPTX2 in patients with delirium compared to non-AD controls, but not when compared to the AD group." (PMID 38566855, 2024). "This analysis included serum levels of NFL and tTau, along with the ratio of serum NFL and CSF NPTX2, which were all significantly elevated in the delirium cohort compared to non-AD controls." (PMID 38566855, 2024). "Both SNAP-25 and NPTX2 have not been studied in delirium yet." (PMID 38566855, 2024). "Consequently, the ratio of neurodegeneration (represented by NFL) to synaptic dysfunction (represented by NPTX2) did not improve the differentiation of delirium from non-AD controls compared to NFL alone." (PMID 38566855, 2024). "Subsequently, we analyzed whether a ratio of neurodegeneration to synaptic dysfunction (specifically, NFL compared to SNAP-25 or NPTX2 and tau compared to SNAP-25 or NPTX2) would more effectively differentiate patients with delirium from control groups (AD and non-AD)." (PMID 38566855, 2024).
dermatitis (1 paper, 2022). An inflammatory process affecting the skin. "DCP-treated NPTX2 KO mice also had a lower dermatitis score and transepidermal water loss (TEWL: an index of the skin barrier function)." (PMID 35501343, 2022).
diabetes (1 paper, 2025). "This study is significant as it represents the first effort to evaluate the association between serum NPTX2 levels and cognitive performance in individuals with diabetes." (PMID 40694319, 2025). "This study is the first to evaluate the association between serum NPTX2 levels and cognitive performance in individuals with diabetes." (PMID 40694319, 2025). "In conclusion, cognitive function was significantly lower in geriatric patients with diabetes than in controls, and serum NPTX2 levels were significantly associated with cognitive performance." (PMID 40694319, 2025). "Given NPTX2’s established role in synaptic plasticity and its dysregulation in neurodegenerative diseases, it may also be implicated in the cognitive complications of diabetes." (PMID 40694319, 2025). "Given the potential influence of metabolic disorders such as diabetes, serum NPTX2 levels may reflect both central and peripheral sources." (PMID 40694319, 2025). "NPTX2 levels correlated positively with MoCA and MMSE scores and negatively with diabetes duration, patient age, and the presence of microvascular complications." (PMID 40694319, 2025).
dyslipidemia (1 paper, 2025). "The PSCI and PSNCI groups also have significant differences in dyslipidemia, NIHSS score on admission, mRS score at discharge, and serum NPTX2 (p < 0.05)." (PMID 39924979, 2025).
familial Alzheimer disease (1 paper, 2025). A degenerative disease of the brain that causes gradual loss of memory, judgment, and the ability to function socially. "The downregulation of both proteins occurs during the onset of clinical symptoms in familial Alzheimer's disease, and our analysis found that the downregulation of NPTX2 in CSF corresponds to a downregulation in brain tissue." (PMID 40491829, 2025).
gastrointestinal stromal tumor (1 paper, 2020). "NPTX1 and NPTX2 were reported to cause dysfunction of the PI3K/AKT/mTOR pathway thereby affecting tumor progression in glioma, gastrointestinal stromal tumors (GIST) and subependymal giant cell astrocytoma." (PMID 33013829, 2020).
glaucoma (1 paper, 2024). Increased pressure in the eyeball due to obstruction of the outflow of aqueous humor. "Also, analyzing aqueous humor levels instead of serum levels could provide more relevant insights in revealing any possible association between NPTX2 and glaucoma." (PMID 39917460, 2024). "Further studies with larger sample sizes might help better understand the role of NPTX2 in glaucoma, if any." (PMID 39917460, 2024). "This study aimed to analyze the levels of some of the serum oxidative stress-related biomarkers, in addition to Aβ and NPTX2, in patients with OHT and compare the results to those from patients with primary open-angle glaucoma (POAG) and healthy controls." (PMID 39917460, 2024).
itch (1 paper, 2022). "Here the authors show that neuronal pentraxin 2 upregulated in primary sensory neurons in chronic itch models is required for facilitating excitatory synaptic inputs onto GRPR expressing spinal neurons." (PMID 35501343, 2022). "Further, using several genetic tools we elucidate the role of neuronal pentraxin 2 (NPTX2; also known as NARP), an activity-dependent immediate early gene product, in the facilitation of excitatory synaptic responses in GRPR+ neurons in chronic itch models." (PMID 35501343, 2022).
keloid (1 paper, 2022). An irregularly shaped, elevated mark on the skin caused by deposits of excessive amounts of collagen during wound healing. "Interestingly, NPTX2, a synapse formation-related gene recently implicated in abnormal cell proliferation and migration in multiple cancers, was significantly inhibited in keloids and shBRCA1 normal DF samples." (PMID 36015648, 2022). "Given the previous reports on BRCA1 in chromatin remodeling, we proposed that BRCA1 suppression in keloids attenuated the accessibility of the NPTX2 enhancer and dismissed the interaction between the NPTX2 enhancer and promoter, resulting in NPTX2 repression." (PMID 36015648, 2022). "BRCA1 binding affinity at the NPTX2 enhancer and the chromatin accessibility in the same region were significantly lower in keloid DFs than in normal DFs, which might contribute to NPTX2 inhibition." (PMID 36015648, 2022). "Considering the difficulties of the current therapeutic method in eradicating keloid and the potential role of NPTX2 inhibition in keloid formation, we proposed the development of NPTX2 agonist might represent a novel option for keloid clinical treatment." (PMID 36015648, 2022). "BRCA1 binds directly to an amplification region associated with the NPTX2 promoter in normal DFs but not in keloid DFs." (PMID 36015648, 2022). "Here, we report that alterations in chromatin accessibility may underlie keloid formation, and BRCA1 suppression might contribute to the regulation of keloid formation by manipulating the accessibility of the amplifier by NPTX2." (PMID 36015648, 2022). "We performed a BRCA1 CUT&Tag-seq in keloids and normal DFs to further investigate the regulatory relationship between BRCA1 and NPTX2." (PMID 36015648, 2022). "As a result, consistent with the signal landscape at NPTX2, the binding signal of BRCA1 at TP63 is lower in keloid DF than normal DF and the chromatin is denser at the corresponding region in keloid DF." (PMID 36015648, 2022).
memory impairment (1 paper, 2023). "NPTX2, which expresses on GABAergic neurons inhibiting excitatory pyramidal neurons, was downregulated in the frontopolar cortex of AD patients, which causes the excitatory/inhibitory imbalance of memory impairment." (PMID 37822109, 2023).
Obesity (1 paper, 2022). Accumulation of substantial excess body fat. "Studies have provided evidence for the association of Nptx2 abnormalities and sleep disorders, which are highly associated with obesity." (PMID 35805082, 2022).
pancreatic adenocarcinoma (1 paper, 2023). "Initially, analysis of pancreatic adenocarcinoma TCGA data confirmed that the methylation levels of BMP3, NPTX2, SPARC, SFRP1 and TFPI2 genes were significantly higher in tumor compared with normal tissue, reinforcing their potential as useful biomarkers." (PMID 37481552, 2023).
proteinopathies (1 paper, 2024). "In this context, NPTX2 may represent an important therapeutic target for TDP-43 proteinopathies, along with STMN2 and UNC13A." (PMID 38355792, 2024).
Seizure (1 paper, 2019). A seizure is an intermittent abnormality of nervous system physiology characterized by a transient occurrence of signs and/or symptoms due to abnormal excessive or synchronous neuronal activity in the brain. "Seizure upregulates the expression of multiple ECM molecules, including tenascin-C, tenascin-R, neuronal pentraxin 2, and hyaluronan." (PMID 31827499, 2019).